TMEM41B (transmembrane protein 41B)
Diseases named in the same sentence as TMEM41B in open-access papers:
TMEM41B is named in the same sentence as 17 diseases in open-access papers, as found by Europe PMC text mining. Sharing a sentence is not in itself a finding about the gene and the disease. The quoted sentences say what the papers report.
viral infection (7 papers, 2021 to 2025). "In humans, single nucleotide polymorphisms in TMEM41B are associated with viral infections such as SARS-CoV-229." (PMID 40038246, 2025). "However, the exact underlying mechanism of TMEM41B in promoting viral infections remains an open question." (PMID 35939522, 2022). "Here, we report that TMEM41B, an ER-resident membrane protein critical for autophagy, lipid metabolism, and viral infection, functions as an ER Ca2+ release channel." (PMID 40038246, 2025). "Upon the cDNA complementation, DENV infection was rescued to levels comparable to the WT cells, reinforcing that both TMEM41B and VMP1 deficiencies are indeed responsible for the observed diminished levels of viral infections." (PMID 35939522, 2022). "Further studies are needed to elucidate the molecular mechanisms by which VMP1 and TMEM41B are recruited in viral infections and how these ER membrane proteins distinctively impact different families of enveloped viruses." (PMID 35939522, 2022). "Despite the repeated identification of TMEM41B, research into its contribution to viral infection has been limited to showing that TMEM41B has a post-entry phenotype and altered localization during infection with SARS-CoV-2." (PMID 34043740, 2021). "Despite this work, there remain many unanswered questions regarding the mechanism of the TMEM41B contribution to viral infection." (PMID 34043740, 2021). "Considering TMEM41B’s ability to release ER Ca2+ to cytosol and the reliance of viruses on host ER for vesicle budding, TMEM41B may control viral infection through its Ca2+ channel activity, which warrants future investigations." (PMID 40038246, 2025). "Surprisingly, MDA5 and RIG-I deficiencies (RIG-I and MDA5 double-KO) did not promote DENV replication in any of the conditions, indicating that the upregulation of the dsRNA sensors is unlikely to be the main contributing factor to the diminished viral infection in TMEM41B KO and VMP1 KO cells." (PMID 35939522, 2022). "In order to understand when in the viral lifecycle TMEM41B may be required for viral infection, we evaluated cellular viability over an infection time course." (PMID 34043740, 2021). "Since we knew that the TMEM41B phenotype was detectible as early as 6 HPI, we rationalized that the loss of TMEM41B was likely not compromising viral infection primarily via suppressing the induction of mature autophagosomes." (PMID 34043740, 2021). "Whether VMP1 and TMEM41B cooperate in augmenting viral infections has yet to be elucidated." (PMID 35939522, 2022). "Apparently, more work is needed to further illustrate how TMEM41B and VMP1 differentiate the upstream signaling from viral infection and autophagy inducers, and designate their distinctive functions under different stress conditions." (PMID 35874956, 2022). "Confocal microscopy revealed that TMEM41B only partially localized with viral markers upon viral infection, and there was no compelling evidence for relocalization or accumulation of the protein at replication complexes." (PMID 34043740, 2021). "Intriguingly, the FA treatment could not rescue HCoV-OC43 infection in both TMEM41B- and VMP1-deficient cells, hinting that deprived cellular FAs in these clonal KO cells might not solely be responsible for diminished viral infection." (PMID 35939522, 2022). "However, because we cannot visualize any replication complexes when TMEM41B is lost, it is possible that a currently unknown, non-lipid mobilization role for TMEM41B prior to replication complex formation is in fact its critical function during viral infection." (PMID 34043740, 2021).
Flavivirus Infections (3 papers, 2022 to 2024). Infections with viruses of the genus FLAVIVIRUS, family FLAVIVIRIDAE. "TMEM41B has been implicated in various pathologies, acting as a host factor in coronavirus and flavivirus infections and as a tumor suppressor in prostate cancer." (PMID 39709500, 2024). "Recently, a molecular marker, TMEM41B (a transmembrane protein), was identified as a pan-flavivirus host factor to explain difference in flavivirus infection among human populations in Asia." (PMID 36560644, 2022).
pulmonary carcinoid tumors (3 papers, 2019 to 2026). "TMEM41B, for example, has been implicated in diverse pathologies, including spinal muscular atrophy, pulmonary carcinoid tumors, and coronavirus infection." (PMID 30933966, 2019). "Furthermore, pathway analysis implicated TMEM41B as being linked to the NF-kB pathway, suggesting its potential role in the deregulation of this pathway in pulmonary carcinoid tumors." (PMID 41596760, 2026). "Notably, TMEM41B mutations have been reported in pulmonary carcinoid tumors." (PMID 39709500, 2024). "In a study on pulmonary carcinoid tumors, TMEM41B, TMEM161B, and TMEM155 were identified as significantly mutated genes through a comprehensive genomic analysis that included whole exome sequencing and whole genome sequencing." (PMID 41596760, 2026).
breast carcinoma (2 papers, 2018 to 2024). "Survival analysis revealed associations of both miR-660-5p and TMEM41B with overall survival in breast cancer patients." (PMID 39709500, 2024). "Our findings revealed a significant increase (p = 0.0077) in TMEM41B protein levels in MDA-MB-231 breast cancer cells compared with those in cells transfected with the NC-miRNA inhibitor." (PMID 39709500, 2024). "To understand the role of TMEM41B in breast cancer, we performed an Ingenuity Pathway Analysis (IPA) with all potential miR-660-5p targets analyzed via RT‒qPCR." (PMID 39709500, 2024). "Future studies should investigate the molecular mechanisms and biological effects of TMEM41B overexpression or knockdown in breast cancer cells." (PMID 39709500, 2024). "The role of TMEM41B in breast cancer remains poorly understood." (PMID 39709500, 2024). "Further exploration of the miR-660-5p/TMEM41B axis could provide valuable insights into its therapeutic potential and clinical relevance in breast cancer management." (PMID 39709500, 2024). "Therefore, further investigations are needed to elucidate the molecular mechanism by which miR-660-5p regulates TMEM41B in breast cancer cells." (PMID 39709500, 2024). "We identified and validated TMEM41B as a target of miR-660-5p in breast cancer cells, which aligns with previous findings that miR-660-5p promotes breast cancer progression by targeting TET2 and activating the PI3K/AKT/mTOR pathway and the miR-660-5p/TFCP2/CDKN1A pathway." (PMID 39709500, 2024). "The TMEM41B encodes the transmembrane protein 41B, and its functional role in breast cancer progression is not known." (PMID 30404658, 2018). "The analysis of TMEM41B did not reveal any potential signaling pathways associated with breast cancer or any other process, and we found no prior reports in the literature regarding the role of this gene in breast cancer." (PMID 39709500, 2024). "Additionally, we identified TMEM41B as a direct target of miR-660-5p in breast cancer cells." (PMID 39709500, 2024). "Survival curves revealed a significant correlation (p = 0.0083) between TMEM41B levels and RFS in breast cancer patients (n = 4929)." (PMID 39709500, 2024). "In addition to TMEM41B, we identified LIFR among the potential targets of miR-660-5p, which has previously been reported as a tumor suppressor in breast cancer metastasis." (PMID 39709500, 2024).
insomnia (2 papers, 2020 to 2023). A sleep disorder characterized by difficulty in falling asleep and/or remaining asleep. "KEGG and GO analyses enrichment for four nerve–related proteins with differential levels in the warm acupuncture treated group were Prolargin, NMDA receptor synaptonuclear-signaling and neuronal migration factor, transmembrane protein 41B and Microtubule-associated protein 1B to adjust insomnia." (PMID 32249904, 2020).
metabolic dysfunction-associated steatohepatitis (2 papers, 2022 to 2026). Metabolic dysfunction-associated steatohepatitis (MASH, formerly known as nonalcoholic steatohepatitis or NASH) is a type of fatty liver disease. "Loss of hepatic TMEM41B or VMP1 results in severe defects in VLDL secretion and leads to the rapid development of metabolic dysfunction-associated steatohepatitis (MASH) in mice." (PMID 41539605, 2026). "In vivo mouse models involving ablation of TMEM41B in liver have shown that knockout of these proteins can lead to rapid development of non-alcoholic steatohepatitis (NASH) and systemic dyslipidemia, though this has not been explored yet with ATG9." (PMID 35509327, 2022).
spinal muscular atrophy (2 papers, 2019 to 2025). A motor neuron disease that affect the muscles, and characterized by muscle weakness and atrophy resulting from progressive degeneration and irreversible loss of the anterior horn cells in the spinal cord (i.e., lower motor neurons) and the brain stem nuclei. "The loss of TMEM41B causes spinal muscular atrophy (a neurodegenerative disease) in worms and mice." (PMID 40038246, 2025).
dengue virus infection (1 paper, 2022). "We further provided evidence that these metabolic roles contribute to TMEM41B and VMP1 essentiality in dengue virus infection." (PMID 35939522, 2022). "Here, we dissected the role of TMEM41B and VMP1 in dengue virus infection, showing that both these proteins are crucial for the normal functionality of mitochondria and the regulation of cellular metabolites." (PMID 35939522, 2022).
Hepatic steatosis (1 paper, 2026). Steatosis is a term used to denote lipid accumulation within hepatocytes. "Restoring VMP1 in Tmem41b KO mice and TMEM41B in Vmp1 KO mice partially corrected defective VLDL secretion and hepatic steatosis in these single KO mice, respectively." (PMID 41638479, 2026).
lung carcinoma (1 paper, 2022). "We further generated clonal TMEM41B KO and VMP1 KO cell lines using human lung carcinoma epithelial cells, A549 cells, to demonstrate that these phenotypes were not limited to only a specific cell type." (PMID 35939522, 2022).
prostate carcinoma (1 paper, 2024). A carcinoma that arises from epithelial cells of the prostate gland. "TMEM41B has been reported to be a tumor suppressor in prostate cancer." (PMID 39709500, 2024).
steatosis (1 paper, 2026). Increased lipid within the cytoplasm of cells. "Loss of hepatic Tmem41b impaired very low-density lipoprotein (VLDL) secretion, with steatosis, inflammation, and fibrosis, whereas hepatic TMEM41B overexpression mitigated these effects." (PMID 41638479, 2026).
infection (17 papers, 2021 to 2025). The state of being infected such as from the introduction of a foreign agent such as serum, vaccine, antigenic substance or organism. "ER Ca2+ overload also downregulates CD5, lowering the activation threshold of TMEM41B-deficient T cells and leading to heightened T cell responses during infections." (PMID 40038246, 2025). "Conversely, the increased responsiveness of TMEM41B-deficient T cells implies that targeting TMEM41B or ER Ca2+ represents a novel strategy to amplify T cell response during infections." (PMID 40038246, 2025). "Intriguingly, TMEM41B-deficient cells were observed to have heightened innate immune responses after infection." (PMID 35308381, 2022). "Infection of all nine cell lines with HCoV-229E revealed that, again, TMEM41B knockout significantly reduced viral RNA by 24 hours post-infection (by ~3 orders of magnitude) in a similar manner to loss of the viral receptor ANPEP." (PMID 34043740, 2021). "The CRISPR/Cas9 screens have recently revealed that TMEM41B is a pan-flavivirus host factor; it has also been identified that in addition to ZIKV, YFV, HCV, WNV, and DENV-2, several other members of the Flaviviridae family require TMEM41B for causing infection." (PMID 37891676, 2023). "In another interesting genome-wide CRISPR KO study, Transmembrane Protein 41B (TMEM41B) was shown to be required for infection and replication of several mosquito-borne and tick-borne flaviviruses, making it a pan-flavivirus host factor." (PMID 36298718, 2022). "TMEM41B was also shown to be critical for infection across multiple cell types, including mosquito C6/36 cells." (PMID 35308381, 2022). "We characterize the localization of TMEM41B during infection and provide evidence for a role promoting appropriate lipid localization in infected cells." (PMID 34043740, 2021). "Among other identified host factors, we focused on TMEM41B and showed that this protein is required for the infection by CoV and other viruses." (PMID 34871328, 2021). "Infection of cells harboring our N-terminal TMEM41B construct however, revealed little overlap of TMEM41B with the vRNA replication marker double-stranded RNA (dsRNA)." (PMID 34043740, 2021). "Future work will be required to answer these questions, as well as define if different coronaviruses all require TMEM41B for the same biological activities during infection." (PMID 34043740, 2021). "Confocal microscopy analysis indicated that dsRNA formation and TGEV N protein accumulation were inhibited almost entirely in TMEM41B KO cells by 3 h post-infection (hpi) upon TGEV infection." (PMID 34871328, 2021). "Our mouse infection model provides strong evidence that knocking out the TMEM41B gene can inhibit viral infection and delay the progression of a CoV disease." (PMID 34871328, 2021). "Transmembrane protein 41B (TMEM41B) was found to be a bona fide host factor involved in infection by CoV and three additional virus families." (PMID 34871328, 2021). "In particular, host protein transmembrane protein 41B (TMEM41B) is necessary for infection of SARS-CoV-2, as well as seasonal coronaviruses HCoV-OC43, -NL63, and -229E." (PMID 34361915, 2021). "Among these, transmembrane protein 41B (TMEM41B) was one of the most important host factors required for infection by SARS-CoV-2 and other seasonal coronaviruses (HCoV-OC43, HCoV-NL63, and HCoV-229E)." (PMID 34835064, 2021). "Despite high or higher viral RNA levels present at 1 hour post-infection (HPI) (representing the initial viral inoculum) viral replication was undetectable during the first 10 hours of infection in TMEM41B KO cell lines." (PMID 34043740, 2021). "We found that upon MHV-A59 infection, TMEM41B+/− mice had significantly delayed disease progression and had significantly reduced virus titers." (PMID 34871328, 2021).
infection (continued). "In addition, infection enriched ER scramblases TMEM41B/VMP1 (regulators of autophagy, LD biogenesis and phospholipid equilibration), indicating that they likely interact with these CE-rich LDs." (PMID 41306517, 2025). "Subsequently, we investigated the influence of TMEM41B on T cell response to infection." (PMID 40038246, 2025). "Moreover, TMEM41B, which is involved in synaptic transmission in motor circuit neurons, is a host dependency factor for infection by multiple flaviviruses and coronaviruses." (PMID 38712102, 2024). "Moreover, TMEM41B, which is involved insynaptic transmission in motor circuit neurons, is a host dependencyfactor for infection by multiple flaviviruses and coronaviruses (84, –, 87)." (PMID 39377586, 2024). "We observed very little HCoV-229E mediated CPE at any timepoint, indicating that loss of TMEM41B was likely blocking some aspect of the initial infection and not spread of the virus." (PMID 34043740, 2021). "The function of human TMEM41B is unknown but it has been identified as being required for autophagosome formation and as a host factor required for infection with flaviviruses as well as SARS-CoV-264,65." (PMID 34934166, 2021). "However, despite apparent differences in how the host factor is co-opted during infection, our lipid mobilization model for how TMEM41B contributes to coronavirus replication complex formation is ultimately similar to the model proposed for flaviviruses." (PMID 34043740, 2021). "According to this study, they identified the vacuole membrane protein 1 (VMP1), transmembrane protein 41B (TMEM41B), and TMEM64 as host factors required for infection by all these coronaviruses." (PMID 36851792, 2023). "The authors found TMEM41B interacts and colocalizes with ZIKV NS4A and YFV NS4B during infection, which is supported by the previous identification of ZIKV NS4B’s interaction with TMEM41B." (PMID 35308381, 2022). "Notably, both TMEM41B and VMP1 are essential for the infection of various viruses, including SARS-CoV-229–31." (PMID 40038246, 2025). "Surprisingly, TBK1 was pre-activated in both TMEM41B KO and VMP1 KO cells prior to infection." (PMID 35939522, 2022). "Interestingly, TMEM41B seems to be an absolutely required factor for SARS-CoV-2, and probably also flaviviral infection, possibly by facilitating a membrane curvature that is beneficial for viral replication." (PMID 35901096, 2022). "The role of TMEM41B in the SARS-CoV-2 life cycle is not unique to coronaviruses, as TMEM41B is also important for infection by flaviviruses (for example, Zika virus (ZIKV))." (PMID 34835064, 2021). "Looking for a non-structural role for TMEM41B during infection, we provide evidence that TMEM41B likely controls lipid trafficking which is important for virally-induced replication complex formation." (PMID 34043740, 2021). "We have also shown minor viral inhibitory effects from beta-oxidation and autophagy inhibitors, and while there is likely an early, primary role for TMEM41B during infection, there could be multiple, non-mutually exclusive TMEM41B-dependent cellular functions important for viral replication." (PMID 34043740, 2021). "Compared to the wild-type (WT) cells, we observed that both TMEM41B KO and VMP1 KO cells were wholly protected from cytolytic infection of flaviviruses and HCoV-OC43, but not alphaviruses." (PMID 35939522, 2022).
cancer (3 papers, 2022 to 2024). A tumor composed of atypical neoplastic, often pleomorphic cells that invade other tissues. "Similarly, TMEM147 and TMEM41B are transmembrane proteins associated with the pathogenesis of various cancers." (PMID 38365771, 2024). "Similarly, DHA down-regulated genes potentially associated to a low OS rate and poor prognosis in GBM such as ERLIN2 and TMEM41B that can inhibit cancer cell growth and metastasis." (PMID 38429759, 2024).
TMEM41B also shares sentences with these, for which no sentence is quoted: neoplastic diseases (2 papers); neurodegenerative disease (1); Obesity (1).